PBK (PDZ binding kinase)
Diseases named in the same sentence as PBK in open-access papers (continued):
Sharing a sentence is not in itself a finding about the gene and the disease.
cancer (continued). "T-LAK cell-originated protein kinase (TOPK), also known as PBK, is a serine/threonine kinase that plays significant roles in cancer process through the mediation of cell proliferation, survival, differentiation, and metastasis." (PMID 40647365, 2025). "Extensive research has highlighted the role of PDZ-binding-kinase (PBK), a PSD95/Discs-large/ZO-1 domain (PDZ)-binding kinase, as a crucial protein kinase in various cancers 6-8." (PMID 39628686, 2024). "In fact, PBK can act on a variety of downstream molecules, such as p38, H3, H2AX, ERK1/2, MKP1, and Prx1, thus promoting the occurrence of cancer, development, metastasis, and drug resistance." (PMID 38460944, 2024). "In the pan-cancer TMB correlation analysis correlation, PBK was highly correlated with the TMB of LUAD." (PMID 37993518, 2023). "TOPK, which is also named PBK (PDZ-binding kinase), has increasingly been considered to be a specific target for cancer therapy." (PMID 36167821, 2022). "PBK/TOPK expression was positively correlated with the expression of DNA mismatch genes and methyltransferase expression, in the majority of cancers except CHOL and UCS." (PMID 34603451, 2021). "T-lymphokine-activated killer cell-originated protein kinase (TOPK, also known as PDZ-binding kinase or PBK) plays a crucial role in cell cycle regulation and mitotic progression and has mainly been described in cancer." (PMID 34576118, 2021). "Our results suggest that in some cancers such as KIRC and LIHC, PBK overexpression can affect patient prognosis by increasing immune cell infiltration." (PMID 34859058, 2021). "PBK was closely related to TMB, MSI, and immune checkpoint genes in various cancers, and patients with higher expression of PBK in KIRC, LGG, and LIHC had higher TIDE scores and lower immune responses in the predicted results." (PMID 34603451, 2021). "However, it remains unclear how PBK regulates paclitaxel‐induced cancer cell death." (PMID 32237067, 2020). "Among these genes, PBK and NEK2 have previously been suggested as biomarkers for aggressive disease in several types of cancer." (PMID 28978135, 2017). "Given the aberrant expression of PBK/TOPK in a variety of cancer types, we decided to investigate the expression of PBK/TOPK in a panel of prostate cell lines." (PMID 25909225, 2015). "Depletion of PBK by PBK shRNA in MDA-MB-231 cells significantly inhibited cell proliferation, indicating an important role of PBK in the cancer cell proliferation." (PMID 25745361, 2015). "Previously, PBK/TOPK, a serine-threonine kinase and a member of MAPKK family, has been shown to play important roles in both normal and cancer cells." (PMID 26081429, 2015). "PBK stimulates AKT-dependent cell migration/invasion by relieving the PTEN-dependent suppressive effect, indicating its crucial role in cancer metastasis." (PMID 25745361, 2015). "Mechanistically, inhibition of PBK was found to induce G1 cell-cycle arrest through activation of the PI3K-Akt-IKK signaling pathway, suppress cell survival signals while promoting pro-apoptosis signaling, and inhibit cancer cell migration and invasion." (PMID 38596293, 2024). "Furthermore, it appears that GPSM2, through the “PBK/TOPK-LGN/GPSM2” pathway, can significantly contribute to cell growth, making it a potential target for cancer therapy." (PMID 38674408, 2024). "A CRISPR-based KO study showed that the expression of PBK/TOPK is not critical for cancer cell proliferation." (PMID 35203508, 2022). "Studies have shown that PBK expression is increased in various cancers compared with normal tissues." (PMID 35065633, 2022). "Moreover, PBK expression was strongly correlated with TMB, MSI, and certain immune checkpoints’ expression across various cancer types, while being negatively correlated with the immune infiltration." (PMID 34859049, 2021).
cancer (continued). "PBK, a dual-specificity serine/threonine kinase, plays an important role in the activation of the Raf/MEK/ERK pathway to promote cell proliferation, colony formation, and cancer development." (PMID 33431797, 2021). "Collectively, our findings describe a novel PBK/MSL1/CD276 signaling axis, which may play an important role in immune evasion of NPC and may be targeted for cancer immunotherapy." (PMID 33431797, 2021). "Moreover, [18F]FE-OTS964 was the first PBK/TOPK inhibitor to be used for imaging purposes and proved useful in the continued investigation of the pharmacology of PBK/TOPK inhibitors and the biology of PBK/TOPK in cancer patients." (PMID 33670114, 2021). "Our results indicated that PBK expression may affect the TMB and MSI levels in different cancers and their immunotherapy responses." (PMID 34859049, 2021). "To clarify the association between PBK expression and specific immune cell types in pan-cancer, we calculated the immunocyte compositions of all TCGA patients using the CIBERSORT algorithm and then explored their correlation with different PBK expression levels." (PMID 34859049, 2021). "Although PBK expression has been shown to correlate with proliferation of cancer cells, PBK silencing does not prevent progression through the cell-cycle." (PMID 18847459, 2008). "To find a molecular explanation for the increased invasion as a function of PBK/TOPK expression, we examined vital downstream effectors, such as the matrix metalloproteinases, MMP-2 and -9, which together are known to play a key role in metastatic development in human cancer patients." (PMID 25909225, 2015). "A link between PBK and EGFR has not been reported in GBM, although a functional relationship has been observed in other cancers." (PMID 26295306, 2015).
infection (5 papers, 2008 to 2023). The state of being infected such as from the introduction of a foreign agent such as serum, vaccine, antigenic substance or organism. "In the current study, phosphorylation of PBK S59 was downregulated following SVA infection, and the significance should be further explored in the future." (PMID 35154063, 2022). "During the late stage of infection, day 18, PbK infected mice exhibited higher levels of TER119+ EryMP (170.9±93.0), CD11b+ MMP (330.4±117.7) and CD45+ LMP (609.3±205.1)." (PMID 24651155, 2014). "The knock-down of the four kinases p38alpha, PKN1, NEK2 and PBK evoked apoptosis as determined via caspase 3 activation compared to the control infection (p < 0.005)." (PMID 18816379, 2008).
hematological malignancies (2 papers, 2015 to 2023). "PBK/TOPK is a substrate of cdc2/cyclin B that can promote mitosis, and PBK/TOPK protein is upregulated in a variety of hematological malignancies, which is important for the proliferation and malignant transformation of hematological tumors." (PMID 37810967, 2023).
colorectal (1 paper, 2021). "For example, PBK facilitates transformation by upregulating and activating ERK2 through an increase in AP-1 (c-Jun) transcriptional activity and increased tumorigenesis of HCT116 colorectal cancer." (PMID 33431797, 2021).
gastrointestinal tumors (1 paper, 2021). "PBK, AURKB, KIF11, and PLK1 confirmed that they are closely related to the occurrence and progression of gastrointestinal tumors, including HCC." (PMID 34200261, 2021).
hematologic neoplasms (1 paper, 2021). "Although PBK/TOPK was upregulated in a variety of primary hematologic neoplasms, it was strongly downregulated in differentiated HL-60 cells after stimulation with phorbol ester (TPA)." (PMID 33670114, 2021).
PBK also shares sentences with these, for which no sentence is quoted: esophageal squamous cell carcinoma (7 papers); skin inflammation (6); dermatitis (4); prostate adenocarcinoma (4); renal cell carcinoma (4); skin cancer (4); Burkitt lymphoma (3); chordoma (3); pancreatic cancer (3); acute kidney injury (2); adrenocortical carcinoma (2); benign prostate hyperplasia (2); central nervous system lymphoma (2); cervical squamous cell carcinoma (2); chronic kidney disease (2); ischemic stroke (2); malignant glioma (2); multiple myeloma (2); myocardial ischemia (2); myocarditis (2); renal fibrosis (2); testicular germ cell tumor (2); adenocarcinoma (1); Alcoholism (1); amyloid (1); Atrophy (1); bladder urothelial carcinoma (1); bone tumors (1); breast adenocarcinoma (1); breast invasive carcinoma (1).
A further 41 diseases each share a sentence with PBK in 1 paper.